PDK4 (pyruvate dehydrogenase kinase 4)
Diseases named in the same sentence as PDK4 in open-access papers (continued):
Sharing a sentence is not in itself a finding about the gene and the disease.
bladder cancer (11 papers, 2020 to 2025). "We further examined PDK4 expression in different stages of human bladder cancer to evaluate the association between PDK4 and tumor prognosis." (PMID 36362028, 2022). "To determine the underlying mechanism of PDK4 in bladder cancer, we evaluated the expression of migration- and invasion-related proteins, p-ERK p-SRC, and p-JNK." (PMID 36362028, 2022). "For instance, the overexpression of PDK4 in high-grade bladder cancer makes the co-administration of DCA with cisplatin cause a dramatic reduction in tumor growth compared to DCA or cisplatin alone." (PMID 34830434, 2021). "Upregulation of PDK4 is observed in high-grade invasive bladder cancers compared with low-grade bladder cancers, and Knockdown or inactivation of PDK4 delays cell proliferation and sensitizes bladder cancer cells to cisplatin." (PMID 40612109, 2025). "Prior research indicates that blocking the effect of PDK4 with some drugs slows the growth of bladder cancer cells." (PMID 36980540, 2023). "Previous data from our lab indicate the pan-PDK inhibitor dichloroacetate (DCA) or acute genetic knockdown of PDK4 blocks proliferation of bladder cancer (BCa) cells." (PMID 36980540, 2023). "To screen for changes in PDK4-related proteins in bladder cancer, we performed a comparative proteomic analysis using PDK4 knockdown cells." (PMID 36362028, 2022). "In this study, we demonstrated that PDK4 is involved in the proliferation, migration, and invasion of bladder cancer cells." (PMID 36362028, 2022). "We then suppressed PDK4 expression in bladder cancer cell lines, which resulted in suppressed metastasis as seen in the reduced number of migrating and invading cancer cells." (PMID 36362028, 2022). "Based on our results, PDK4 plays a critical role in the metastasis and growth of bladder cancer cells through changes in ERK, SRC, and JNK." (PMID 36362028, 2022). "To verify the relationship between PDK4 and tumorigenesis in bladder cancer, we suppressed PDK4 expression as a first step." (PMID 36362028, 2022). "IHC results showed that T3 bladder cancer tissues had higher levels of PDK4 expression than normal tissues." (PMID 36362028, 2022). "In quantitative analysis, PDK4 mRNA expression in T3 bladder cancer tissues was twofold higher than that in normal tissues." (PMID 36362028, 2022). "Taken together, these results demonstrate the functional and physical relationship between PDK4 and tumor growth and metastasis in bladder cancer." (PMID 36362028, 2022). "We confirmed the suppressed mRNA and protein expression of PDK4 in two bladder cancer cell lines, T24 and J82, by siRNA transfection using qPCR and Western blot analyses." (PMID 36362028, 2022). "As in human bladder cancer specimens, PDK4 expression was correlated with the T category in bladder cancer patients." (PMID 36362028, 2022). "In bladder cancer cell lines, PDK4 silencing resulted in a lower rate of cell migration and invasion." (PMID 36362028, 2022). "In the present study, we evaluated the role of PDK4 in bladder cancer and its related protein changes." (PMID 36362028, 2022). "To evaluate the role of PDK4 in bladder cancer, we suppressed PDK4 expression, and downregulated PDK4 reduced the migratory capacity and invasiveness of bladder cancer cells by modulating p-ERK, p-SRC, and p-JNK." (PMID 36362028, 2022). "Moreover, PDK4 was upregulated in bladder cancer tissues and its expression was further increased in advanced tumor tissues." (PMID 36362028, 2022). "Our results show that PDK4 was overexpressed in human bladder cancer tissues." (PMID 36362028, 2022). "In addition, we examined the relationship between PDK4 and tumor growth in vivo, as well as in human bladder cancer specimens." (PMID 36362028, 2022). "Furthermore, we evaluated the overexpression of PDK4 in human bladder cancer samples and its expression pattern in different cancer stages." (PMID 36362028, 2022). "First, we observed elevated PDK4 expression in high-grade bladder cancers." (PMID 36362028, 2022).
bladder cancer (continued). "Thus, we evaluated the expression of PDK4 in human bladder cancer tissues and performed proteomic analysis to identify PDK4-related proteins in bladder cancer." (PMID 36362028, 2022). "Thus, the present study evaluated the PDk4 protein as a biomarker in bladder cancer by investigating its function in this disease." (PMID 36362028, 2022). "Another study demonstrated that PDK4 is substantially upregulated in bladder cancer cell lines, and inhibition of PDKs combined with cisplatin therapy could further reduce tumor volume in vivo." (PMID 34589439, 2021). "Another study demonstrated PDK4 is substantially activated in high grade bladder cancer cell lines, and inhibition of PDKs combined with cisplatin therapy could further decrease tumor volume in vivo." (PMID 34589439, 2021). "In addition, a PDK4 knockdown xenograft model showed reduced bladder cancer growth in nude mice." (PMID 36362028, 2022). "In the meantime, another study on bladder cancer has stressed the anti-metastatic effects of PDK4 via the ERK and JNK pathways in bladder cancer cells." (PMID 39399421, 2024). "In a validated mouse model of bladder cancer, mice that did not express PDK4 were found to have larger tumors than mice expressing PDK4 at later points of tumor progression." (PMID 36980540, 2023). "It has been reported that PDK4 played oncogenic effects in CRC and bladder cancer." (PMID 37340443, 2023). "Human samples with bladder cancer had lower expression of PDK4 than those without bladder cancer." (PMID 36980540, 2023). "However, the effect of PDK4 on bladder cancer has not been studied." (PMID 36362028, 2022). "Furthermore, in CRC and bladder cancer, the mitochondrial pyruvate fails to undergo the TCA cycle due to the inhibition of pyruvate dehydrogenase (PDH) by the overexpressed pyruvate dehydrogenase kinase 4 (PDK4)." (PMID 36618350, 2022).
cervical cancer (10 papers, 2020 to 2023). A primary or metastatic malignant neoplasm involving the cervix. "IGF2BP3 is associated with chemotherapy resistance in cervical cancer by regulating PDK4 mRNA stability." (PMID 37298373, 2023). "In Cervical Cancer, demonstrated that m6A regulates glycolysis in cancer cells through pyruvate dehydrogenase kinase 4 (PDK4)." (PMID 35186927, 2022). "In cervical cancer cells, N6‐methyladenosine positively regulates glycolysis via the induction of PDK4, providing new insights into the function of PDK4 in cancer therapy." (PMID 35656815, 2022). "Another study discovered that the YTHDF1/eEF-2 complex and IGF2BP3 increase the translation elongation and mRNA stability of pyruvate dehydrogenase kinase 4 to control glycolysis in cervical cancer cells." (PMID 36091006, 2022). "Consistently, IGF2BP3 and YTHDF1, the readers of PDK4 mRNA, significantly increased in cervical cancer tissues as compared with that in the normal control samples." (PMID 32444598, 2020). "At this point, we explored the possibility of a link between m6A methylation, PDK4 and cervical cancer development." (PMID 32444598, 2020). "Consistently, cervical cancer patients with increased expression of PDK4 showed reduced disease-free survival (DFS) and overall survival (OS)." (PMID 32444598, 2020). "Together, these data suggested that PDK4 was involved in m6A regulated glycolysis and progression of cervical cancer." (PMID 32444598, 2020). "Clinical analysis confirmed the positive correlation between Mettl3 and PDK4 in cervical cancer tissues." (PMID 32444598, 2020). "Moreover, YTHDF1/eEF-2 complex and IGF2BP3 positively promote the translation elongation and mRNA stability of pyruvate dehydrogenase kinase 4 (PDK4) to regulate glycolysis of cervical cancer cells." (PMID 34392306, 2021). "The expression of Mettl3 was positively correlated with the PDK4 mRNA in cervical cancer patients." (PMID 32444598, 2020). "In cervical cancer (CC) cells, YTHDF1 accelerates m6A-augmented glycolysis and cancer progression by promoting translational elongation of pyruvate dehydrogenase kinase 4 (PDK4) mRNA and stabilization of hexokinase 2 (HK2) mRNA." (PMID 36999016, 2023). "However, ectopic overexpression of PDK4 attenuated this effect and reduced DOX sensitivity in cervical cancer cells." (PMID 35186927, 2022).
colorectal cancer (7 papers, 2018 to 2026). A primary or metastatic malignant neoplasm that affects the colon or rectum. "In colorectal cancer, METTL16 plays a key role in promoting glycolytic metabolism and tumor progression by regulating the expression of key glycolytic enzymes, such as SOGA1 and pyruvate dehydrogenase kinase 4 (PDK4)." (PMID 41459114, 2026). "Furthermore, TGF-β has been shown to mediate the activation of pyruvate dehydrogenase kinase 4 (PDK4) by 5-fluorouracil, and the activation of PDK4 leads to colorectal cancer cells that are highly chemoresistant." (PMID 30487436, 2018).
laryngeal carcinoma (7 papers, 2019 to 2024). Carcinoma that arises from the laryngeal epithelium. "Xu and colleagues revealed that lncRNA PCAT1 enhances proliferation and glycolysis of laryngeal cancer cells through miR-182/PDK4 axis." (PMID 38554157, 2024). "PCAT19 also acts as a competing endogenous RNA, in which it sponges the miR-182 to regulate the PDK4, and consequently modulates the glycolysis and mitochondrial respiration in laryngeal cancer cell lines." (PMID 35415316, 2022). "It was shown that LncPCAT19 promotes the proliferation and poor prognosis of larynx carcinoma, and that the LncPCAT19-mediated regulation in laryngeal cancer cells occurred through the miR-182-mediated facilitation of the mitochondrial PDK4 expression." (PMID 31416244, 2019). "Moreover, PCAT19 can promote the proliferation of laryngeal cancer cells through the miR-182/ PDK4 axis." (PMID 35480331, 2022). "By modulating the miR‐182/PDK4 axis, PCAT19 promotes the proliferation of laryngeal carcinoma cells." (PMID 34925511, 2021).
glioblastoma (6 papers, 2015 to 2023). The most malignant astrocytic tumor (WHO grade IV). "Gene expression analysis of 3D glioblastoma spheroids has shown increased expression of pyruvate dehydrogenase kinase 4 (PDK4) involved in the suppression of mitochondrial activity." (PMID 36945054, 2023). "PDK4 was shown to be abundant in patient glioblastoma compared to normal tissue, and indirectly reducing its expression through shRNA targeting the RelA subunit of NF-kB resulted in reduced growth of xenografts in nude mice." (PMID 26576332, 2015). "In addition, carnosine’s anti-neoplastic effect in glioblastoma cells was shown to be accompanied by increased expression of pyruvate dehydrogenase kinase 4 (PDK4)." (PMID 31247000, 2019). "Therefore, we compared the effect of carnosine on glioblastoma cell viability, PDK4 expression and signaling molecule phosphorylation with the PI3K inhibitor Ly294,002 and the mTOR inhibitor rapamycin in two cell lines derived from glioblastoma." (PMID 31247000, 2019). "As a result, AToMI analysis revealed AKT and mitochondrial pyruvate dehydrogenase kinase PDK1 and PDK4 as kinase targets of staurosporine derivatives UCN-01, CEP-701, and K252a that synergized with PP2A activation across heterogeneous glioblastoma cells." (PMID 35963891, 2022).
lung adenocarcinoma (6 papers, 2014 to 2025). A carcinoma that arises from the lung and is characterized by the presence of malignant glandular epithelial cells. "In cancer patients with lung adenocarcinoma, the survival curve analysis indicated that the population with higher expression of PDK4, FMO2, or FABP4 is correlated with better survival rates." (PMID 29285217, 2017). "We divided lung adenocarcinoma patient samples into PDK4-high (PDK4 expression above median) and PDK4-low (PDK4 expression below median)." (PMID 25379179, 2014). "Similarly, PDK4 has been reported to be highly expressed in cisplatin-resistant lung adenocarcinoma." (PMID 34250255, 2021). "Additionally, miR-182 is dysregulated and inversely correlated with PDK4 in human lung adenocarcinomas, and miR-182 suppressed PDK4 expression and promoted lung tumorigenesis." (PMID 32489458, 2020). "In our study, PDK4 played a potential tumor suppressor role in lung adenocarcinoma." (PMID 29285217, 2017). "Thus, lung adenocarcinoma patients whose tumors have low PDK4 expression showed reduced overall survival." (PMID 25379179, 2014). "The expressions of PDK4, FMO2, and FABP4 are significantly downregulated in lung adenocarcinoma compared to normal lung tissue in several datasets, and this phenomenon was also observed in GSE10072 array." (PMID 29285217, 2017). "The analysis of the effects from each gene expression on survival outcome indicated that 6 genes (AGR2, SPDEF, CDKN2A, CLDN3, SFN, and PHLDA2) play oncogenic roles, and 7 genes (PDK4, FMO2, CPED1, GNG11, IL33, BTNL9, and FABP4) act as tumor suppressors in lung adenocarcinoma." (PMID 29285217, 2017).
cardiomyopathy (5 papers, 2013 to 2024). A disease of the heart muscle or myocardium proper. "The results suggested genes (Pdk4, Igf1r, Lipe, Serpine1, and Bcl2l1) targeted cardiovascular diseases including cardiomyopathies, ventricular dysfunction, etc.." (PMID 38961143, 2024). "The same was observed for PDK4 and UCP3, genes that exacerbate cardiomyopathy." (PMID 23593350, 2013).
colitis (5 papers, 2023 to 2025). Inflammation of the colon. "Loss of PDK4 function can delay colitis development and reduce T cell activation and aerobic glycolysis." (PMID 40375928, 2025). "Increased expression of PDK4 has been associated with colitis, with its substrate accumulating in CD4+ T cells of patients with inflammatory bowel disease." (PMID 40375928, 2025). "PDK4 upregulation drives pathogenic Th17 responses in IBD mucosa; PDK4 inhibition ameliorates colitis in murine models." (PMID 41476956, 2025). "In addition, CD4+ T cells deficient in PDK4 induce less intestinal inflammation in both DSS-induced colitis and naïve T cell adoptive transfer colitis." (PMID 37809060, 2023). "PDK4 deletion in CD4+ T cells attenuates colitis through metabolic regulation, underscoring the need for comprehensive investigation of PDK2’s immunometabolic role in IBD." (PMID 40821793, 2025). "In colon biopsy samples from IBD patients, CD4+ T cells show markedly increased pyruvate dehydrogenase kinase (PDK) expression, and PDK4 inhibition alleviates intestinal inflammation in a DSS-induced murine colitis model." (PMID 41476956, 2025). "The anti-inflammatory effects of PDK4 suppression have been demonstrated in DSS-induced colitis animal models and naïve T cell transfer colitis models in vivo." (PMID 37809060, 2023). "In line with this, the experimental DSS-induced colitis model also displays the significantly upregulated expressions of PDK4 and p-PDHE1α after DSS challenge." (PMID 37809060, 2023). "Certainly, PDK4 KO mice were found to be more resistant to DSS-induced colitis." (PMID 37809060, 2023). "Of note, DSS-induced colitis mouse model was constructed to demonstrate that the expression of key anoikis genes, namely H2-DMa, CX3CL1, and CFB were significantly upregulated, while PDK4 was evidently downregulated." (PMID 40115777, 2025). "Furthermore, treatment with the pharmacological PDK4 inhibitor, GM-10395, compromises CD4+ T cell activation and attenuates DSS-induced colitis." (PMID 37809060, 2023).
diabetic cardiomyopathy (5 papers, 2022 to 2025). Diabetic cardiomyopathy is a disorder of the heart muscle in people with diabetes. "Among the genes that exhibited differential expression, 58 were linked to diabetic cardiomyopathy while eight genes were linked to mitochondria, specifically the gene encoding for the mitochondrial protein pyruvate dehydrogenase–PDK4." (PMID 38547044, 2024). "Combined with genes associated with diabetic cardiomyopathy, Pdk4 was validated as the target gene that may play a key role in mediating diabetic cardiomyopathy during exercise." (PMID 38547044, 2024). "After the two exercise models, three genes related to diabetic cardiomyopathy overlapped: Col11a1, Pdk4, and Comp." (PMID 38547044, 2024). "While the regulation mechanism of these miRNAs with PDK4 in diabetic cardiomyopathy remains unclear, and the effect of miR-3084b-3p and miR-6323 in cardiovascular disease has yet to be reported." (PMID 38547044, 2024). "Combined, the decreased cardiac expressions of Pdk4 and Ucp3, reduced cardiac glycogen content, and reversion of diabetic cardiomyopathy in O304-treated STZ mice provide evidence that O304 restores cardiac metabolic flexibility and glucose oxidation, i.e., cardiac efficiency, in these mice." (PMID 37626210, 2023). "For example, inhibition of the transcription factor forkhead box O1 prevents transcription of Pdk4, which encodes for PDHK4, thereby increasing myocardial glucose oxidation and alleviating the diastolic dysfunction associated with experimental diabetic cardiomyopathy in mice." (PMID 36211560, 2022). "FOXO activation in HFD mice has been demonstrated to increase PDK4 expression, while FOXO knockout enhanced glucose oxidation and improved cardiac function in a diabetic cardiomyopathy model." (PMID 40362448, 2025). "Additionally, a separate study identified an AKT-p38-FOXO signaling pathway, where activation of AKT and p38 in a diabetic cardiomyopathy model promoted FOXO nuclear translocation, leading to the upregulation of PDK4." (PMID 40362448, 2025).
dilated cardiomyopathy (5 papers, 2015 to 2025). Cardiomyopathy which is characterized by dilation and contractile dysfunction of the left and right ventricles. "A missense mutation in the titin gene (TTN) and a splice-site mutation in the pyruvate dehydrogenase kinase 4 gene (PDK4) have been associated with dilated cardiomyopathy (DCM) in Dobermanns from the United States." (PMID 40080479, 2025). "A splice site mutation in the canine pyruvate dehydrogenase kinase 4 (PDK4) gene has been shown to be associated with the development of dilated cardiomyopathy (DCM) in Doberman Pinchers (DPs)." (PMID 32127618, 2020). "Association of the TTN and PDK4 variants with dilated cardiomyopathy." (PMID 40080479, 2025). "This includes the IGFBP5 gene candidate variant for bald thigh syndrome in sighthounds, SLC7A9 and SLC3A1 gene variants associated with cystinuria in Bulldogs, as well as PDK4 and TTN gene risk variants for dilated cardiomyopathy (DCM) in Dobermans." (PMID 36848397, 2023).
Glucose intolerance (5 papers, 2015 to 2025). Glucose intolerance (GI) can be defined as dysglycemia that comprises both prediabetes and diabetes. "According to the interaction network of PDK4 from the String database, DLD is involved in caloric restriction (CR)-preventable mitochondrial ROS in yeast aging process, and PDHX reduction is related to aging diseases, such as Alzheimer’s disease, glucose intolerance, and cancer." (PMID 35372351, 2022).